IRF4 (interferon regulatory factor 4)
Diseases named in the same sentence as IRF4 in open-access papers (continued):
Sharing a sentence is not in itself a finding about the gene and the disease.
cancer (80 papers, 2012 to 2025). A tumor composed of atypical neoplastic, often pleomorphic cells that invade other tissues. "Analysis in this way revealed, as observed with CRISPR, that depletion of IRF4 results in reduced cancer cell fitness associated with cell death and apoptosis." (PMID 36219477, 2023). "The catalog of somatic mutation in cancer (COSMIC v97) contains 146 somatic missense variants identified in hematopoietic cancers affecting the whole IRF4 gene." (PMID 37809068, 2023). "Studies have also shown that IRF4 directs Treg differentiation and immunosuppression in human cancers, and IRF4+ Tregs are associated with poor prognosis." (PMID 34020619, 2021). "Numerous evidences have implicated IRF4 as an oncogenic driver and potential target for inhibition by anti-cancer agents." (PMID 29346274, 2018). "Since IRF4 is a “context-dependent” factor, it is necessary to analyze the patterns of gene expression associated with IRF4 in individual cancer types." (PMID 25207815, 2014). "These advantages encouraged us to conduct this meta-analysis of all published articles investigating the association between IRF4 gene polymorphisms and cancer risk." (PMID 24906573, 2014). "In this study, we have first profiled molecular signatures associated with IRF4 expression in associated cancers, by analyzing existing gene expression profiling datasets." (PMID 25207815, 2014). "To derive a more precise estimation of the relationship between the rs12203592 and rs872071 IRF4 polymorphisms and cancer risk, we performed a meta-analysis of all available case-control studies." (PMID 24906573, 2014). "Given the possible of the IRF4 gene product in the immune response and carcinogenesis, numerous investigators have studied the possible association between the IRF4 polymorphisms and cancer risk, but the results are somewhat inconclusive." (PMID 24906573, 2014). "MTAP and IRF4 have been implicated in cancer and immune responses respectively and IRF4 is also important in pigmentation." (PMID 23796690, 2013). "Variants within IRF4, exemplified by rs12203592, might influence these cancers' vulnerability or progression given their regulatory function." (PMID 40134047, 2025). "Recent GWAS have reported that variants at several sites within the IRF4 gene may be implicated in the risk of cancer." (PMID 24906573, 2014). "The lymphocyte-specific IRF4 plays a pivotal role in immune evasion, particularly in the context of cancer, and has garnered significant attention in recent years." (PMID 40733503, 2025). "Interferon regulatory factor 4 (IRF4) serves as one of the genetic markers for identifying TLSs in cancers, and it fulfills a complex role in immune regulation." (PMID 40607252, 2025). "The lymphocyte-specific transcription factor interferon regulatory factor 4 (IRF4) is a key player in immune evasion in cancers, with the complex mechanism(s) being barely understood." (PMID 40733503, 2025). "Among the different genes within hub CHA regulatory units, MYC and IRF4 are unique as they are transcription factors, immediate early response genes and are involved in cancer." (PMID 37019979, 2023). "Data demonstrate that CAR T cells with reduced IRF4 levels retain anti-cancer cell activity under repetitive challenge conditions for a longer period than conventional CAR T cells." (PMID 37287982, 2023). "To extend a CAR T cell anti-cancer cell response upon repetitive antigen encounter, we reduced IRF4 levels by expressing an IRF4-specific shRNA in CAR T cells." (PMID 37287982, 2023). "In a recent study, IRF4 emerged as crucial regulator of CAR T cell exhaustion upon repetitive encounter of cancer cells." (PMID 37287982, 2023). "In conclusion, numerous studies have demonstrated the importance of IRF4 in normal development, immunity, and cancers." (PMID 36077849, 2022). "Accordingly, various studies have demonstrated the functional requirement of IRF4 for cancer cell survival and proliferation." (PMID 36077849, 2022).
cancer (continued). "As well-described for c-MYC, both IKZF1 and IRF4 are involved in the development of cancer, including CRC." (PMID 33478584, 2021). "In conclusion, our study demonstrates that IRF4 is a novel regulator of PMN-MDSCs in cancer and that c-Myc is the transcriptional target of IRF4 in MDSCs." (PMID 33708218, 2021). "It has been recently shown that either cancer or SARS-CoV-2 infection mediates the activity of the IRF4-BATF pathway activating IRF-mediated transcription." (PMID 34716309, 2021). "Recent studies have found that the abnormal expression of IRF4 is closely related to the occurrence of various malignant tumors (lymphoma, multiple myeloma, etc.)and autoimmune diseases." (PMID 33708218, 2021). "As recent review reported several pathways in Treg from cancers including Foxp3, IRF4, PI3/AKT/FoxO axis, Helios, Eos, Nr4a, Bach2, E proteins and their inhibitor of DNA-binding (Id) counterparts, STAT3, and NF-kB." (PMID 34084175, 2021). "The silencing of interferon regulatory factor 4 (IRF4), a transcription factor overexpressed by cHL cells and involved in cancer cell proliferation and survival, decreases CCL5 secretion." (PMID 32630699, 2020). "Aggregating the mean methylation levels of all CpGs, IRF4 is significantly hypermethylated in BC as well as in almost every other cancer type within the TCGA collection." (PMID 32855526, 2020). "Downregulation of cMYC and of cMYC-dependent signatures in MM cells (e.g., IRF4 and IRF4-dependent oncogenic targets) have been proposed as pivotal effectors of BETi-mediated activity in this cancer." (PMID 27903272, 2016). "We found 81 non-silent mutations (35 from LG-ESSs and 46 from UUSs) that included 15 putative cancer genes catalogued in cancer-related databases, including PPARG and IRF4 mutations." (PMID 26429873, 2015). "To date, only limited targets including miR-155, IRF5, Blimp1, CCNB1, BCL6, CDK6, Myc, and several others have been identified as IRF4 targets in cancers." (PMID 25207815, 2014). "In future pursuits, we will combine with other strategies including cell culture systems to identify IRF4-regulated networks in individual cancer contexts." (PMID 25207815, 2014). "Clearly, identification of IRF4-specific gene regulation networks will improve our understanding of its functional roles in distinct cancer contexts." (PMID 25207815, 2014). "Since the cGAS-STING pathway is pivotal in cancer immune surveillance, IRF4 may also play a role in the evasion of the cGAS-STING-mediated innate immune response in EBV latency, at least by regulating their expression." (PMID 40733503, 2025). "Interferon regulatory factor 4 (IRF4) was initially identified as a key controller in lymphocyte differentiation and function, and subsequently as a dependency factor and therapy target in lymphocyte-derived cancers." (PMID 38880659, 2024). "We here aimed at improving anti-cancer cell functionality of CAR T cells by reducing IRF4 levels." (PMID 37287982, 2023). "Through bioinformatics analysis, we found that FSCN1 could interact with IRF4, which is involved in the oncogenesis of multiple cancers." (PMID 37491232, 2023). "However, under conditions of repetitive challenge with cognate cancer cells, CEA-28ζ-I1 CAR T cells with IRF4 downregulation showed superior cancer cell elimination compared with conventional CAR T cells." (PMID 37287982, 2023). "IRF4 levels rise in response to stimuli or when IRF4 upstream proteins are overexpressed in cancer." (PMID 36611989, 2023). "Genes including the HLA gene family, B2M, and IRF4 might be the key genes involved in the anticolon cancer response of CD8+ T cells by regulating cholesterol metabolism." (PMID 34858500, 2021).
cancer (continued). "Higher expression of IRF4+ Tregs was related to poor prognosis for different cancers." (PMID 34109184, 2021). "We first aimed to confirm in silico the methylation status of IRF4 in cancer." (PMID 32855526, 2020). "Knockdown of Gls1 increased the expression of Cdkn1a and Cdkn1b and decreased the expression of some critical oncogenes for cancer cell survival, such as c-Myc, Cdk4, and NfκB, as well as some genes which are essential for MM cell survival, such as Irf4, Prdm1, Csnk1α1, and Rassf5." (PMID 31666930, 2019). "Since this rhythmic alternative splicing is directly correlated with the clock, we hypothesise that changes in clock expression are correlated with the AS pattern of IRF4, hence affecting the cancer phenotype." (PMID 31363108, 2019). "In cancer, they can upregulate transcription of key oncogenes such as cMYC, IRF4, and BCL-2." (PMID 27903272, 2016). "To address whether the mutations found in our study could be causally implicated in ESS development, we queried the cancer Gene Census and found four mutations (SRGAP3, EBF1, IRF4 and PPARG)." (PMID 26429873, 2015). "There were also gene sets related to cancer signaling pathways (MYC, STAT3, and CDH1) or genes moderately involved in cancer (IRF4, SOX4, and EZH2), as well as some associated with various aspects of cancer such as cell transformation, metastasis, and response to therapeutics." (PMID 25122487, 2014). "We initially checked the expression levels of IRF4 in different cancer cell lines." (PMID 25207815, 2014). "In summary, IRF4 may function as a cancer-promoting gene in ccRCC." (PMID 40607252, 2025). "We found IRF4 may play a role in the transformation of fibrosis into cancer." (PMID 36797470, 2023). "IRF4 might be a novel regulator of PMN-MDSC development in cancer." (PMID 35993041, 2022). "In addition, IRF4 plays a role in the regulation of Treg differentiation in human cancer." (PMID 33468159, 2021). "For example, in the hypomethylation-specific function “immune response”, IRF4, which negatively regulates toll-like-receptor signalling that is central to the activation of innate and adaptive immune systems, was observed to be hypermethylated in all five cancer types." (PMID 22970311, 2012). "Genes at two of these loci, HERC2/OCA2 and IRF4, are involved in pigmentation, while the third, CLPTM1L/TERT, is a known cancer driver." (PMID 40495383, 2025). "Given the significant relevance of cancer cells with low antigen densities evading a CAR T cell attack, we next evaluated the impact of IRF4 downregulation on the killing of targets with low antigen density." (PMID 37287982, 2023). "However, the importance of IRF4 levels in cancer progression remains unknown." (PMID 37341064, 2023). "The phenotypes of cancer cells are CD20+, BCL2+, and IRF4/MUM-1+ with active proliferation (MIB-1/Ki 67++)." (PMID 32528871, 2020). "For example, ASCL1, CDX2, IRF4, MITF, NKX2-1, PAX8 and SOX2 were pinpointed as outliers in cell lines of their corresponding cancer tissue origins." (PMID 31050342, 2019). "Of the genes tested in plasma, BCAT1, GRASP, IKZF1, IRF4, SDC2, SEPT9 and SOX21 exhibited high sensitivity (≈55% or greater) for detection of methylated ctDNA in cancer patients." (PMID 27983717, 2016). "Under normal conditions, BET family proteins perform transcription regulatory functions, while in cancer, they can upregulate aberrant transcription of key oncogenes such as cMYC, BCL-2, and IRF4." (PMID 27903272, 2016). "For example, in a study of Interferon regulatory factor 4 (IRF4) with effector Treg differentiation and immune suppression in cancer, Foxp3EGFP-Cre-ERT2 mice were crossed with Irf4-floxed mice to allow for the specific deletion of Irf4 in Foxp3+ cells following TAM treatment." (PMID 36009853, 2022). "Among these genes, only BATF3 and IRF4 were highly co-expressed with BATF in the majority of cancers, which suggested that BATF might carry out its role by cooperating with BATF3 and IRF4." (PMID 35573731, 2022).
cancer (continued). "In summary, genes including the HLA gene family, B2M, IRF4, and STAT5A might be the key genes involved in the anticolon cancer response of CD8+ T cells via regulation of cholesterol metabolism." (PMID 34858500, 2021). "Genes including the HLA gene family, B2M, IRF4, and STAT5A might be the key genes involved in the anticolon cancer response of CD8+ T cells through the regulation of cholesterol metabolism." (PMID 34858500, 2021). "From gene profiling analysis, we showed that the most important signal molecules which are critical for most cancer cell or MM survival, such as MYC, E2F, RAS, NFκB, IRF4, mTORC1, and others were significantly down-regulated when Gls1 level was reduced or its activity inhibited." (PMID 31666930, 2019). "Further study on the interaction between IRF4 and the IFN-inducible genes including IFI27 and IFI44 may disclose the mechanism through which IRF4 confers resistance to IFN treatment of vial cancers by regulating their expression." (PMID 25207815, 2014). "Interestingly, multiple genes encoding cell surface immune checkpoint receptors and their ligands were transcriptionally regulated by IRF4, including PD-L1 (CD274), PD1 (CD279), CTLA4 (CD152), B7-2 (CD86), LAG3 (CD223), and PD-L2 (CD273), in these virus-infected cancer cells." (PMID 40733503, 2025). "Starting with a relatively similar distribution of CD45RO+ CD62L+ central memory T cells and CD45RO+ and CD62L- effector memory cells, both CAR T cells with and without IRF4 down-regulation shifted from central memory to effector memory T cells during the consecutive rounds of cancer cell challenge." (PMID 37287982, 2023). "Studying the pathophysiology of autosomal dominant IRF4 protein variants and their impact on transcriptome, epigenome, and chromatin structure organization will provide important new insights into IRF4 function and might have implications for treatments of IEI and possibly even cancer." (PMID 37809068, 2023). "Based on these results, we speculate that genes including the HLA gene family, B2M, IRF4, and STAT5A that may be involved in EBV infection and cell adhesion molecule pathways play important roles in the anticolon cancer response of CD8+ T cells by regulating cholesterol metabolism." (PMID 34858500, 2021). "However, during three rounds of cancer cell challenges we did not detect loss of functional capacities or major differences in effector-memory phenotypes or the expression of exhaustion markers, except transient upregulation of TIM-3, along with IRF4 downregulation." (PMID 37287982, 2023). "Although the other two genes in the 3-ceRNA signatures, IRF4 and IL2RB, are not yet functionally characterized in GBM, they play essential roles in immune responses and cancer." (PMID 28241741, 2017).
infection (61 papers, 2008 to 2025). The state of being infected such as from the introduction of a foreign agent such as serum, vaccine, antigenic substance or organism. "Nevertheless, a skewed IRF-4/RF-5 balance cannot entirely explain the severe defects we observed in IRF-5-deficient CD8 T cells during the chronic phase of infection." (PMID 40494997, 2025). "Mice deficient in Irf4 in CD11c+ cells secrete less IL-4, IL-5, and IL-13 both in the SI and colon after infection with the parasite Schistosoma mansoni, and a similar outcome is observed after infection with T. muris and Nippostrongylus brasiliensis." (PMID 41028655, 2025). "After competitive T cell transfer, CD4+ T cells heterozygous for Irf4 mutation were already impaired in generating Th2 and Th17 cells responses to infection and in their accumulation in the intestinal tract of recipient mice." (PMID 37469513, 2023). "Induced deletion of the remaining Irf4 allele after infection further reduced frequencies of intestinal CD4+ T cells in the colon but not in the small intestine." (PMID 37469513, 2023). "Further studies of GI-tract-resident cells, including myeloid and lymphoid cells in particular, should make it possible to decipher the molecular and cellular mechanisms by which human IRF4 haploinsufficiency underlies WD upon infection by Tw." (PMID 29537367, 2018). "IRF4 encodes interferon regulatory factor 4, a member of the interferon regulatory factor family of transcription factors that are essential in interferon regulation in response to infection." (PMID 28241741, 2017). "IRF4 deficient mice were impaired in the control of both pathogens, failed to mount Th17 and Th2 cell responses and showed impaired recruitment of T helper cells to the intestine, the infection site of both pathogens." (PMID 37469513, 2023). "Moreover, the module E of greater accessibility occurring at day 21 post infection contains ChARs adjacent to the genes encoding for IRF4 and TOX, two well-known TFs driving T-cell exhaustion." (PMID 33579927, 2021). "In order to test if the Irf4 gene dosage also influences the formation of Treg cells, percentages of these cells were analyzed in Irf4+/+, Irf4+/- and Irf4-/- mice under homeostatic conditions and after infection with ovalbumin-recombinant listeria (LmOVA)." (PMID 40726986, 2025). "Nine days after infection, the NCG mice receiving IRF4-deficient ILC3s developed more severe illness than those receiving Irf4f/f-ILC3 cells." (PMID 40585371, 2025). "Both Th17 and Tregs play an essential role in the infection experiments and are also affected by the conditional deletion of IRF4." (PMID 40585371, 2025). "The results of our study provide evidence that myeloid knockout of IRF4 increases the immune response by reducing infection-induced MDSCs in S. japonicum infection, thereby alleviating the inhibitory effect of T cell proliferation and activation." (PMID 39609883, 2024). "These are involved in the regulation of immune responses to infection and inflammation and IRF4 and IL-10 interact to regulate immune responses." (PMID 38762479, 2024). "Our results showed that the serum ALT level of IRF4-KO mice decreased significantly after infection with S. japonicum." (PMID 39609883, 2024). "In the study reported here, we examined the impact of IRF4 myeloid knockout on infection outcomes across various organs, along with the progression of MDSC activation and differentiation in mice infected with S. japonicum." (PMID 39609883, 2024). "To investigate the effect of the IRF4 gene on mice infected with S. japonicum, we infected WT and IRF4-KO mice with S. japonicum cercariae through abdominal skin and then sacrificed the mice 6–7 weeks after infection for testing." (PMID 39609883, 2024). "Eight days post-infection, Irf4-/- mice had higher citrobacter titers in the liver, indicating that IRF4 was required for restriction of bacterial dissemination." (PMID 37469513, 2023).